RNU6-147P (RNA, U6 small nuclear 147, pseudogene)
Gene: Small nuclear RNA gene on chromosome 20 (49,972,106 to 49,972,212, forward strand). Ensembl gene ENSG00000206710.
Homologues: Orthologues: chimpanzee U6 (97% identical), mouse Gm25257 (82% identical), mouse Gm24268 (79% identical), pig U6 (77% identical), rabbit U6 (69% identical). Paralogues in human: RNU6-22P (89% identical), RNU6-348P (89% identical), RNU6-1060P (88% identical), RNU6-116P (88% identical), RNU6-1201P (88% identical), RNU6-19P (88% identical), RNU6-47P (88% identical), RNU6-949P (88% identical), RNU6-1011P (87% identical), RNU6-1181P (87% identical), RNU6-12P (87% identical), RNU6-1303P (87% identical), and 1286 more.